IFNG (interferon gamma)
Diseases named in the same sentence as IFNG in open-access papers (continued):
Sharing a sentence is not in itself a finding about the gene and the disease.
viral infection (continued). "As a result, conditions with Th1 immune activation such as cancers, viral infections, or IFNγ therapy lead to lowered serum tryptophan levels, increased kynurenine/tryptophan ratio, and possibly a shift in the balance from serotonin to kynurenine biosynthesis." (PMID 31631951, 2019). "The interferon gamma (IFN-γ) are cell signals associated with increased elaboration, given viral infections an innate antiviral response." (PMID 31805646, 2019). "Those with multiple viral infections had less marked interferon (IFN)-γ responses in cord blood PBMC to PHA stimulation, and less decline over a year in such IFNγ responses." (PMID 30941335, 2019). "We have identified a novel regulatory role for IFNγ as a suppressor of neutrophil proliferation during viral infection." (PMID 29352287, 2018). "IFNγ is used for treating cancers and viral infection, however, the therapeutic efficacy of IFNγ is highly variable among different types of cancer." (PMID 29855346, 2018). "In contrast, PCT production is down-regulated in viral infections, probably due to increased interferon gamma production." (PMID 29891780, 2018). "Here, we describe a novel regulatory role for the cytokine IFNγ that is critical for preventing fatal encephalitis after viral infection." (PMID 29352287, 2018). "This work demonstrates a mechanism by which IFNγ, a prototypical pro-inflammatory cytokine, can exert anti-inflammatory effects on innate inflammatory responses during viral infection of the CNS." (PMID 29352287, 2018). "Our data suggest that during homeostasis, intestinal microbiota condition the respiratory immune system so that during a viral infection production of pro-inflammatory cytokines, like IFNγ, is regulated." (PMID 30042764, 2018). "One of the important cytokines involved in suppressing viral infections is Interferon Gamma (IFNG), which has clinical implications in preventing the development of chronic hepatitis, liver cirrhosis, and hepatocellular carcinoma." (PMID 29531550, 2017). "The naïve control group displayed substantial numbers of IFNγ-secreting cells, most probably representing T cells induced by the live virus infection given 5 days prior to sacrifice." (PMID 28749414, 2017). "The results indicate that IFNγ and TNFα still play important roles to control virus infection in this study." (PMID 29070073, 2017). "The IL-12– and IL-18–mediated activation of MAIT cells is likely to have desired consequences during, for example, a local virus infection, in which enhanced IFNγ production can help limit virus replication." (PMID 28742082, 2017). "Anti-HMGB1 also significantly reduced the viral infection in the lungs of RAGE deficient mice, and significantly increased IFNα4 and IFNγ expression in the lung compared to mice treated with the isotype control." (PMID 28099113, 2017). "In the super-SILAC detected DEPs, consistent prediction of IFNG was computed out; in addition, other known viral infection relevant pathways, such as IFNA2, IFNB1 and TLR, were also deemed up-stream activators by IPA." (PMID 28117408, 2017). "Noteworthy, the cytokines of crucial importance for clearing a viral infection, such as the Th1 cytokines IFNγ, and IL‐15, the pro‐inflammatory cytokines IL‐1β, IL‐6, TNFα, and TNFβ/lymphotoxin, were downregulated." (PMID 28805308, 2017). "NK cells display at least two major effector functions to control viral infection: they can directly attack infected cells through cell-to-cell contact, but they also secret a variety of antiviral cytokines such as interferon-gamma (IFNγ)." (PMID 27513564, 2016). "At 48 hpi, the infected cells comprised 17.05% of the IFNα group and 5.58% of the IFNγ group, indicating that goose IFNγ protein conferred more resistance against viral infection." (PMID 27438848, 2016). "In contrast, nestin+ cells were maintained at all dpi in CD46+ mice in comparison to mock-infected mice, suggesting that IFNγ preserves this population during a CNS viral infection." (PMID 27178303, 2016).
viral infection (continued). "Overall, this study implicates IFNγ as one cytokine involved in preserving NSPCs during viral infections and other inflammatory conditions." (PMID 27178303, 2016). "Cell surface expression of CEACAM1 is induced by viral infection and inflammatory cytokines such as IFNγ." (PMID 26909604, 2016). "Within 12 hours of secondary viral infection, both IFNα and IFNγ became readily detectable within the plasma of infected mice." (PMID 27580079, 2016). "As the canonical Th1 cytokine, IFNγ is vital for innate and adaptive immunity against viral infection." (PMID 27150912, 2016). "Indirect damage arising from acute or chronic viral infection has been frequently attributed to the antiviral immune response, with IFNγ and CD8+ T cells playing a major role." (PMID 27695457, 2016). "Clinically, there is a clear susceptibility to viral infections and three of the four patients (#2, 3, and 4) have low levels of both IFNγ‐producing NK cells and CD4+ T cells, known to predispose to recurrent and persistent viral infection." (PMID 27896283, 2016). "IFNα and IFNγ, two types of antiviral cytokines, were also up-regulated after viral infection, activating the JAK-STAT signaling pathways and inducing the transcription of ISGs, including Mx, OASL2, GBP, IFIT5, and TRIM25." (PMID 27916934, 2016). "Th1 cells are induced in response to pathogens, such as viral infections, and are characterized by the production and release of interferon gamma (IFN-γ)." (PMID 26583100, 2015). "With IRF1 knock down, a significant increase in EBOV GP/rVSV RNA was observed 24 hours following infection, consistent with the importance of IRF1 expression in controlling virus infection by IFNγ." (PMID 26562011, 2015). "As expected and in light of our findings, the M(IFNγ + LPS, TNFα) signature was enriched in genes altered under intracellular parasites and bacterial, or viral infection, as well as under pro-inflammatory conditions (LPS or IFNγ)." (PMID 26302899, 2015). "Using EBOV GP/rVSV, we next sought to assess the relative contribution of IFNγ and TNFα in inhibiting virus infection." (PMID 26562011, 2015). "Interferon-gamma production has been reported to play an important role in the immune response against numerous viral infections." (PMID 25788896, 2015). "Novel activity-based probes and native gel analysis revealed that immunoproteasome activities are specifically and rapidly induced by IFNγ treatment in respiratory cells in vitro and by virus infection of the lung in mice." (PMID 25989070, 2015). "IFNγ is a cytokine secreted by T- and NK-cells and important for both innate and adaptive immune responses against viral infections." (PMID 26344619, 2014). "IFNγ is one of the consequences of viral infections and stimulates the expression of histocompatibility complex (MHC) proteins and immunoproteasome subunits to facilitate presentation of antigens to CD8+ T cells." (PMID 24827739, 2014). "Using an ovalbumin (OVA) modeling system, we found viral infection and IFNγ enhanced the presentation of TAA to CD8+ T cells through the canonical endogenous pathway of MHC I presentation." (PMID 24827739, 2014). "T cells producing these multiple cytokines simultaneously are believed to be better equipped to control viral infection than those producing IFNγ alone." (PMID 25051027, 2014). "The well documented role of IFNγ in enhancing CTL activities against viral infection has supported the concept that IFNγ therapy can augment anti-HIV CTL activities in HIV+ subjects." (PMID 24454311, 2014). "While Type I IFNs are largely induced by viral infection of host cells, IFNγ is induced by more generalized antigenic and mitogenic stimulation." (PMID 24454311, 2014). "Levels of IFNγ, a key cytokine in viral infections, were found to be higher in tumor-bearing mice compared to non-tumor bearing mice (white bars compared to grey and black bars)." (PMID 24866126, 2014).
viral infection (continued). "To identify T1D-associated genes that are required for antiviral immunity, we developed an image-based high-throughput assay to measure the contribution of individual genes to IFNγ-mediated inhibition of viral infection." (PMID 25268627, 2014). "We found that even after proper recognition of infected cells by NK cells, the adequate production of IFNγ is crucial to restrain viral infection." (PMID 25473962, 2014). "IFNγ is a Th1-specific cytokine produced by macrophages, NK cells, and other cell types during the onset of viral infection." (PMID 23711280, 2013). "Viral infections are generally associated with the differentiation of IFNγ-, TNFα-, and IL-2-producing Th1 cells, driven by Type I IFN, IL-12, and IFNγ production provided by innate immune cells during viral infections." (PMID 23717308, 2013). "NK cells can limit viral replication directly by lysing virus-infected cells, and are also stimulated during a viral infection through cytokines to produce antiviral cytokines such as interferon-gamma (IFN-γ)." (PMID 23372568, 2013). "While for CEACAM1, CEACAM5 and CEACAM6 an up-regulation by IFNγ and viral infections has been described in epithelial cells, to our knowledge this is the first report that also type I interferons enhance CEACAM1 expression." (PMID 23941132, 2013). "We first examined the mRNA expression levels of AsEomes, IFNγ, CD8α, and granzyme A at different time intervals following bacterial and viral infection in the spleen and head kidney." (PMID 23409078, 2013). "The level of IDO protein present in U251 and SNB19 cells was measured following IFNγ treatment and virus infection." (PMID 22924042, 2012). "On the other hand, IFNγ is known to be a representative cytokine of CD8+ T cells and is also associated with viral infection." (PMID 22413812, 2012). "Similar to viral infections, our functional studies indicate that T1IFNs act redundantly with IFNG to activate mechanisms that protect against malaria disease." (PMID 23144737, 2012). "Inasmuch as antigen presentation and cellular effector activity during a viral infection are regulated by cytokines, we evaluated the levels of serum IL-2, IL- 4, IL-6, IL-10, TNFα and IFNγ from LSIL patients and normal controls." (PMID 22642942, 2012). "The presence of CD8 + IFNγ + lymphocytes is a normal occurrence since the early stages of viral infection." (PMID 22642942, 2012). "We therefore measured IDO mRNA expression by quantitative RT-PCR at 2 and 8 hours following virus infection of IFNγ-treated cells." (PMID 22924042, 2012). "Our in vitro digests utilised immunoproteasomes as they are typically induced within the first day of viral infection by exposure to IFNγ or TNFα." (PMID 21589893, 2011). "Interferon-gamma (IFN-γ) is vital in vaccine-induced immune defense against bacterial and viral infections and tumor." (PMID 21624163, 2011). "Studies of human and mouse iNOS and the associated NO production, have reported that these molecules are often active in concert with IFNγ, to protect against viral infection, however, their role in avian species is less defined." (PMID 21283521, 2011). "In this regard, recent studies have provided evidence for the protective function of IFNγ in neuronal cells after viral infections and excitotoxicity." (PMID 21073708, 2010). "Here we show that CCL3-mediated neutrophil recruitment depends directly on IFNγ signaling, both in the setting of acute virus infection and in response to heterologous CCL3 expression in the respiratory epithelium." (PMID 19298652, 2009). "In addition to viral infections and malignancies, IFNγ is also involved in autoimmune diseases because of its ability to disrupt the immune system homeostasis." (PMID 40264756, 2025). "Moreover, murine cytomegalovirus (mCMV) models have shown that the production of IFNβ and IFNγ in response to viral infection results in the transcriptional downregulation of the sterol biosynthesis pathway in bone marrow-derived macrophages." (PMID 41488671, 2025).
viral infection (continued). "GO (gene ontology) analyses found that these shared upregulated genes belonged to ‘interferon‐gamma response’, ‘type I interferon response’, consistent with the concepts that IFN‐γ and IFN‐I responses are essential to response caused by TB and viral infection, respectively." (PMID 41163794, 2025). "Most pathways classically associated with the macrophage response to viral infection were upregulated in both conditions (MHC-I, M1-differentiation, IFNα, interferon-stimulated genes, and IFNγ) but genes associated with MHC-II antigen presentation were downregulated in infected macrophages." (PMID 40245043, 2025). "While interferon gamma release due to some virus infections may protect from further virus infections at the same time or shortly after, this has neither been described for SARS-CoV-2, in general, nor the current strain specifically." (PMID 41472255, 2025). "However, normal or mildly elevated PCT levels are observed in viral infections due to the inhibitory effect of interferon-gamma on PCT synthesis." (PMID 40217585, 2025). "STAT3 can be activated by IL-6 and interferon-gamma (IFN-γ) by viral infection." (PMID 40006981, 2025). "While CRP may rise in response to various inflammatory stimuli, PCT levels remain low in viral infections due to suppression by interferon-gamma (IFN-γ)." (PMID 40647525, 2025). "Upon viral infection, macrophages are activated by TLRs or primed by IFNγ." (PMID 38965547, 2024). "However, mucosal ILC1s produce IFNγ, which upregulates antiviral genes in the uninfected epithelium, providing a first-line defense against virus infection." (PMID 38684766, 2024). "Our findings demonstrating direct, IL-15-independent effects of IFNε on NK cells are consistent with reports that NK cell expression of the type I IFN receptor (IFNAR) is required to mediate their cytolytic activity and IFNγ production in other sites during viral infections." (PMID 38263527, 2024). "Finally, we evaluated the impact of viral infection on the local immune response by quantifying IFNG and CD163 expression." (PMID 38389522, 2024). "However, the role of type-2 IFN (IFNγ) during viral infection, and in particular, SARS-CoV-2 infection, is less clear." (PMID 38086794, 2023). "Regarding the T cell response factor, the importance of the Th1 response during viral infection is well known, but in our knowledge, a level of IFNγ was never been associated to infection prediction." (PMID 37606852, 2023). "Additionally, in the setting of viral infection and IFNγ treatment, the drugs wortmannin, apilimod, and alpelisib proved too toxic to provide interpretable data related to phosphatidylinositol involvement (not shown)." (PMID 37905813, 2023). "Thus, as concluded from previous animal model studies, the recovery from viral infection and the clearance of viral RNA requires the presence of virus-specific antibodies and interferon gamma (IFN-γ) secretion from T cells." (PMID 36920996, 2023). "Notably, PCT levels are not elevated in response to viral infections due to the inhibitory effect of the interferon-gamma, which is produced during viral infections." (PMID 37760722, 2023). "IFNγ modulates the immune response to viral infection and affects memory T cells." (PMID 37766163, 2023). "Together, our data suggest the MEERvvS TME harbors Treg cells primed to be inflammatory, such that IFNγ induced by viral infection promotes a state of Treg cell fragility, resulting in a less immunosuppressive environment and greater effector function of the newly induced T cell infiltrate." (PMID 37552475, 2023). "These novel findings identify different sources and localization of Ifnγ following viral infection that may impact on subsequent infections and improve our understanding of the generation of both classical and non-classical immune memory." (PMID 37842651, 2023).
viral infection (continued). "In viral infections, interferon gamma inhibits tumor necrosis factor alpha—induced upregulation of endocan expression and these results likely reflect pathophysiological differences in endothelial injury in severe viral infections compared with severe bacterial infections." (PMID 38102316, 2023). "Previously, a low ratio between IFNγ and IL10 has been associated with viral infection." (PMID 36293090, 2022). "In addition, the discovered ability of GMDP to stimulate the production of interferon-gamma can serve as an explanation for the preventive effect in viral diseases." (PMID 35207480, 2022). "PCT synthesis is inhibited by high IFNγ levels due to viral infection." (PMID 35453906, 2022). "When viral infections occur, interferon-gamma (IFN-γ) is released." (PMID 36553115, 2022). "In an animal study, after viral infection in 25(OH)D3-fed mice, the proinflammatory cytokines interleukin-5 (IL-5) and Interferon gamma (IFN-γ) were significantly downregulated, indicating that 25(OH)D3 decreases the production of inflammatory cytokines and viral replication." (PMID 35334804, 2022). "The timing of IL-27 function during virus infection appears paradoxical, as early IL-27 signaling is important for enhancing innate antiviral responses and potentially regulating IFNγ production, but also may attenuate these very responses by increasing IL-10." (PMID 35634328, 2022). "In order to confirm whether the oral and the SL immunization could suppress the inflammatory response incurred through viral infection, pro-inflammatory cytokines, interferon-gamma (IFN-γ) and interleukin-6 (IL-6), levels were assessed in the lung homogenates." (PMID 35888065, 2022). "However, the amount of IFNγ was nearly equal for Ad-WT, XVir-N-31, and XVir-N-31-anti-PD-L1, suggesting that this was a result of virus infection and not limited to OAVs." (PMID 36077380, 2022). "The timing of IL-27 activity may be critical as to whether it increases or decreases IFNγ production systemically during viral infection." (PMID 35634328, 2022). "Some studies suggested that certain children are more prone to be severely infected because of dysregulation of the innate immune response, such as low antiviral interferon-gamma (IFN-y) production in response to viral infection or structural airway pathologies." (PMID 36362786, 2022). "These genes were mainly enriched in virus infection pathways and inflammation pathways, such as response to type I interferon, interferon-gamma-mediated signaling pathway, activation of innate immune response, interleukin 1 mediated signaling pathway, and defense response to virus." (PMID 34561445, 2021). "Impaired interferon gamma (IFN-γ) induction by bronchial epithelial cells in response to viral infections appears to be a common feature in severe COPD and may contribute to susceptibility to viral infections and severe ECOPDs." (PMID 34502194, 2021). "IFNγ plays an important role in the immune response against viral infections." (PMID 34936684, 2021). "In part, this may be due to concerns that use of IFNγ during acute viral disease might exacerbate the hyperinflammatory state that can accompany viral disease in STAT2 deficiency." (PMID 34448086, 2021). "HAdV-C5 establishes a state of persistent viral infection in HDF cells in the presence of IFNα or IFNγ that can be maintained for months without the loss of cell viability." (PMID 34724821, 2021). "Genetically conditioned sex-differences, resulting in a more sensitive and responsive immune system, with a more profound release of cytokines (e.g. interferon-gamma) following a viral infection may contribute to this." (PMID 32271826, 2020). "IFNγ is an important cytokine for innate and adaptive immune response against viral infections." (PMID 32518225, 2020).